SNORD84 (small nucleolar RNA, C/D box 84)
Synonyms: U84
Gene: Small nucleolar RNA gene on chromosome 6 (31,541,101 to 31,541,178, reverse strand). Ensembl gene ENSG00000265236.
Gene Ontology:
Biological process: RNA processing
Cellular component: nucleolus
Homologues: Orthologues: macaque SNORD83 (99% identical), pig SNORD83 (88% identical), mouse Gm22589 (86% identical), rabbit SNORD84 (85% identical), guinea pig SNORD84 (83% identical), rat LOC120099056 (82% identical), dog SNORD83 (79% identical), zebrafish SNORD83 (73% identical), zebrafish SNORD83 (71% identical), zebrafish SNORD83 (69% identical), tropical clawed frog SNORD83 (67% identical). Paralogues in human: SNORD117 (76% identical), SNORD83 (63% identical).